GCG (glucagon)
Diseases named in the same sentence as GCG in open-access papers (continued):
Sharing a sentence is not in itself a finding about the gene and the disease.
diabetes (continued). "Glycemic instability is a serious problem in patients with insulin-deficient diabetes, and it may be due in part to abnormal endogenous glucagon secretion." (PMID 25393115, 2014). "In diabetes, deficiency of insulin in conjunction with glucagon- or catecholamine-stimulated lipolysis increases fatty acid delivery to liver which may lead to ketoacidosis, a life-threatening condition." (PMID 25161769, 2014). "Although much less mentioned, dysregulated glucagon secretion is another key factor that promotes hyperglycemia and diabetes development: loss of glucose inhibition of glucagon secretion leads to increased glucose production from the liver even in the presence of hyperglycemia." (PMID 22046328, 2011). "Consistent with selective β cell ablation in STZ-diabetic pigs, insulin mRNA by RT-PCR was significantly decreased (p<0.0001), somatostatin and pancreatic polypeptide transcript levels were unaltered, while glucagon mRNA showed the characteristic increase associated with diabetes (p<0.0001)." (PMID 18320053, 2008). "The mechanisms of a less efficient effect by GLP-1 to suppress glucagon secretion in diabetes remain unclear but further underline the importance of restoring glucagon hypersecretion in this disease." (PMID 18478125, 2008). "By identifying β-cell loss as the primary driver of impaired glucagon secretion, this work reframes counterregulatory dysfunction as an islet network defect and highlights restoration of intra-islet β-cell signaling as a therapeutic strategy for improving glycemic stability in diabetes." (PMID 42040939, 2026). "In contrast, older populations displayed lower glucagon knowledge, which is a concerning trend, especially since older diabetic patients are at a higher risk for hypoglycemic events and are often less likely to be actively engaged with current diabetes care methods." (PMID 40585626, 2025). "Mouse models of diabetes associated with extreme beta-cell loss have demonstrated that reprogramming occurs in around 2% of islet alpha-cells to allow transdifferentiation to beta-cells, with an intermediate cell phenotype of both glucagon and insulin expression." (PMID 39791735, 2025). "Since genotype at rs7903146 was known in these cohorts, we also show that diabetes-associated genetic variation in TCF7L2 seems to have a greater effect on raising peak glucose concentrations as well as impairing the suppression of postchallenge glucagon concentrations." (PMID 39011323, 2024). "However, current evidence generally agrees that smoking is a risk factor for diabetes, and in particular that nicotine in tobacco has been found to decrease glucose tolerance, lower insulin secretion, and increase insulin resistance and glucagon secretion." (PMID 39647865, 2024). "Certainly, in a case of diabesity, the use of a short-acting glucagon infusion only will aggravate hyperglycaemia; thus, a proper additional insulin therapy would be crucial to maintain euglycaemia and accelerate energy expenditure in patients with insulin-deficient diabetes." (PMID 38579770, 2024). "Primary hypoadrenalism (Addison’s Disease) is associated with Type 1 diabetes and may present in these patients with new-onset hypoglycaemia and decreasing insulin requirements, particularly in long-standing diabetes due to loss of the counter-regulatory hormones, glucagon and noradrenaline." (PMID 37892096, 2023). "Diabetes mellitus is a series of physiological dysfunctions characterized by hyperglycemia associated with abnormalities in carbohydrate, fat, and protein metabolism caused by resistance to insulin action, inadequate insulin secretion, or excessive glucagon production." (PMID 36770960, 2023). "Increased levels of glucagon in the blood can be considered diagnostic criteria for glucagonoma; however, hypergluconemia can also occur in other pathologies such as acute or chronic pancreatitis, liver cirrhosis, renal failure, diabetes, Cushing’s syndrome, stress, trauma and chronic liver failure." (PMID 37628857, 2023).
diabetes (continued). "Additionally, to better understand the effects of macronutrients on the pathogenesis of diabetes, further studies are needed to determine the association of macronutrients substitution with plasma C-peptide, circulating glucagon levels, and amylase involved in glucose metabolism." (PMID 35277013, 2022). "While it was initially proposed that hyperglucagonemia in diabetes results from a loss of insulin inhibitory control on alpha-cell glucagon secretion, an alternative hypothesis is that alpha-cell number and secretory capacity is increased as a compensatory mechanism to enhance beta-cell function." (PMID 35957816, 2022). "First, the mentioned loss of the glucagon response, usually occurring within 5 years after diabetes diagnosis, and the resultant greater exposure to hypoglycaemia may lead to a ‘sudden’ shift of glycaemic thresholds for counterregulatory responses to lower glucose levels." (PMID 35867127, 2022). "In addition to insulin, glucagon also plays a key pathogenic role in the development of diabetes." (PMID 36394315, 2022). "In fact, as stated by the bihormonal hypothesis, diabetes progression may be dependent on both excessive glucagon secretion and insulin deficiency, and the glucagonocentric hypothesis ascribes even more importance to alpha cell dysfunction in diabetic hyperglycemia." (PMID 34659118, 2021). "Thus, there is a dual islet abnormality in diabetes, qualitatively common to both type 1 and type 2: The deficiency of insulin secretion in response to hyperglycemia, and the deficiency of glucagon secretion in response to the lowering of blood glucose by insulin." (PMID 34572493, 2021). "However, one study failed to establish a significant association between residual beta cell function and glucagon responses to hypoglycemia in young people with type 1 diabetes whereas some have found an association between decreasing glucagon responses and diabetes duration." (PMID 34405569, 2021). "It is currently unknown whether the glucagon secretion defects associated with diabetes develop in α‐cells independently of the disruption of β‐cell function or whether they are a consequence of diabetes." (PMID 32716554, 2020). "Our hypothesis is that proteins that associate with glucagon within alpha cell secretory granules will regulate glucagon secretion, and may provide druggable targets for controlling abnormal glucagon secretion in diabetes." (PMID 32117057, 2020). "Therefore, insulin resistance in α cells is associated with glucagon dysregulation in diabetes." (PMID 31357734, 2019). "As high copeptin has been repeatedly shown to be a strong independent risk factor for diabetes, the second aim of our study was to investigate if a reduction of copeptin by increased water intake for 1 week may influence glycemia, insulin or glucagon concentrations." (PMID 29242971, 2019). "Consequently, it is plausible that aging in people with diabetes could be associated with abnormal ratios of glucagon to insulin with a subsequent impact on exercise capacity." (PMID 29720965, 2018). "Thus, our results highlight that inhibition of alpha cell glucagon production is one potential mechanism by which leptin might be effective in controlling hyperglycemia in individuals with diabetes caused by diminished insulin reserve." (PMID 28702245, 2016). "Significance:SLC30A8 diabetes risk alleles may influence glucagon secretion." (PMID 26178371, 2015). "The mechanisms by which TCF7L2 polymorphisms increase diabetes risk and affect the treatment response to insulin secretagogues were thought to be related to impaired incretin-induced insulin secretion, impaired suppression of glucagon or impaired glucagon-like peptide-1 secretion." (PMID 24906949, 2014).
diabetes (continued). "Therefore, we suggest that β-NGF can be helpful as index of that chronic infection stage able to evolve into cirrhosis and, then, HCC while glucagon and IL-18 can be index of the diabetes association that occurs as part of the metabolic syndrome leading to HCC." (PMID 22745767, 2012). "Nearly four decades ago, the bihormonal-abnormality hypothesis established the essential role for glucagon in diabetes, by highlighting the contributions of deficient insulin secretion, development of insulin resistance and increased glucagon secretion to the hyperglycemic state in type 2 diabetes." (PMID 22479612, 2012). "While diabetes research has traditionally focused on β-cells, α-cell dysfunction is critically important, particularly in T1D, where dysregulated glucagon secretion is a prominent feature." (PMID 41550143, 2026). "In patients with type 1 diabetes mellitus, duration of hyperglycemic symptoms was negatively correlated with plasma glucagon levels (ρ = − 0.62, P = 0.0007)." (PMID 41292690, 2026). "In that report, decreased insulin secretion in type 1 diabetes mellitus, but exaggerated insulin response in type 2 diabetes mellitus, was correlated with the exaggerated glucagon response to the arginine challenge test." (PMID 41292690, 2026). "Blood levels of glucagon in diabetes mellitus have been investigated using radioimmunoassays (RIAs)." (PMID 41292690, 2026). "Protein ingestion plays a key role in the secretion of both insulin and glucagon, making it a key regulator of blood glucose levels in health and diabetes." (PMID 41602572, 2026). "This retrospective observational study investigated the association between sleep disorders and alterations in glucose metabolism, insulin secretion, and glucagon regulation in patients with type 2 diabetes mellitus (T2DM)." (PMID 41686553, 2026). "In type 2 diabetes mellitus, positive correlations were also seen between both an exaggerated glucagon response and an estimate of insulin resistance." (PMID 41292690, 2026). "While a SSTR2a is being evaluated as an approach to restoring glucagon counterregulatory failure in rodent models of diabetes, other potential effects of acute and chronic SSTR2a administration on glucose metabolism in T2D on are not known." (PMID 41502124, 2026). "In diabetes, glucagon is typically oversecreted during hyperglycemia but undersecreted during hypoglycemia." (PMID 41502124, 2026). "Although currently in the trial phase, these therapeutic approaches exhibit substantial promise for enabling more precise control over glucagon activity within diabetes management strategies." (PMID 40919135, 2025). "In diabetes, disrupted cAMP signaling leads to impaired insulin secretion and excessive glucagon release." (PMID 40822953, 2025). "Functionally, GLP-1R activation by its endogenous agonist GLP-1 promotes insulin secretion, suppresses glucagon release, slows gastric emptying, and induces satiety, thereby making it a pivotal therapeutic target in type 2 diabetes mellitus (T2DM) and obesity." (PMID 41226200, 2025). "Traditionally regarded as an anti-insulin hormone, glucagon was soon employed in clinical practice to treat insulin-induced hypoglycemic coma in individuals with type 1 diabetes mellitus (T1DM)." (PMID 41149695, 2025). "Similar results showing a small proportion of insulin+/glucagon+ islet cells in normoglycemic conditions with an increase in their proportion in diabetes were obtained in rodents." (PMID 39860066, 2025). "Over the past decades, research has increasingly shifted toward understanding the broader physiological roles of glucagon, particularly its involvement—together with pancreatic α-cells—in the pathophysiology of type 2 diabetes mellitus (T2DM) and obesity." (PMID 41149695, 2025). "This substitution, replacing a polar amino acid with a non-polar one, was predicted to impair the inhibitory activity of PAX4 on the INS and GCG promoters, leading to hyperglycemia and diabetes." (PMID 41153735, 2025).
diabetes (continued). "This would decrease insulin secretion and increase glucagon secretion, a situation similar to that seen in diabetes and starvation." (PMID 40305364, 2025). "Paradoxically, individuals with diabetes exhibit elevated glucagon levels even in the presence of hyperglycemia." (PMID 41149695, 2025). "Hypoglycemia stimulates glucagon secretion in healthy individuals, but this counterregulatory mechanism is impaired in diabetes, leading to continued stimulation of glucagon secretion by hypoglycemia." (PMID 40809178, 2025). "Remarkably all six mice treated with immune sera remained diabetes free (6/6) with intact pancreases and islets expressing insulin and glucagon." (PMID 40760251, 2025). "Dual or triple agonists targeting gut hormones—including GLP‐1, glucagon (GCG), and GIP—offer a promising therapeutic strategy for diabetes by modulating glucagon signaling." (PMID 40919135, 2025). "These insights emphasize the importance of reevaluating glucagon not only as a metabolic hormone, but also as a potential upstream driver of multi-organ complications in diabetes." (PMID 40822953, 2025). "These agents mimic GLP-1, enhancing glucose-dependent insulin secretion, suppressing glucagon release, and slowing gastric emptying to improve glycemic control, as indicated by reduced HbA1c level, a crucial measure in diabetes care." (PMID 40471297, 2025). "Further mechanistic studies are needed to clarify how glucagon-induced mitochondrial stress contributes to the progression of diabetes and its complications." (PMID 40822953, 2025). "Amylin, another gut-related hormone (co-secreted with insulin), also suppresses appetite and glucagon; the amylin analog pramlintide is approved for diabetes, and longer-acting amylin or amylin-plus-peptide co-agonists are advancing in obesity pipelines." (PMID 40871736, 2025). "In this review, we will discuss recent advances in understanding lysosome-mediated autophagy and lysosomal proteins involved in maintaining insulin and glucagon homeostasis, as well as their contributions to the etiology of diabetes." (PMID 39996055, 2025). "GLP-1 agonists are FDA-approved drugs used in the treatment of type 2 diabetes mellitus and obesity as they increase insulin release, decrease glucagon production, enhance proliferation of pancreatic beta cells, and delay gastric emptying." (PMID 40067438, 2025). "Collectively, these investigations aim to refine our understanding of glucagon biology and to explore its therapeutic potential in mitigating multi-organ complications of diabetes." (PMID 40822953, 2025). "DPP-4i extends the half-life of GLP-1, thereby enhancing insulin production and diminishing glucagon release, which leads to improved glycemic control in individuals with type 2 diabetes mellitus (T2DM)." (PMID 40427515, 2025). "Further, this study assessed children during the first year following diabetes diagnosis (selected as a time of systematic CD screening in our practice), when some endogenous insulin and glucagon production remains and can mitigate hypoglycemia." (PMID 40990290, 2025). "Those with diabetes for less than five years were more likely to know about the use of glucagon (p<0.05)." (PMID 40585626, 2025). "Humans with diabetes have been shown to have elevated fasted and postprandial glucagon concentrations and delayed glucagon suppression after a glucose tolerance test compared to healthy individuals." (PMID 40051530, 2025). "Glucagonoma diagnosis requires tumor detection, elevated glucagon levels, and characteristic systemic findings such as rash, diabetes, or hypoaminoacidemia." (PMID 40894446, 2025). "The questionnaire collected demographic data, diabetes-related information, and knowledge regarding glucagon use." (PMID 40585626, 2025). "Deregulation of GNG is a hallmark of type 2 diabetes mellitus (T2DM), driven by hepatic insulin resistance, elevated glucagon levels, and excess circulating free fatty acids." (PMID 40802799, 2025).
diabetes (continued). "Patients with diabetes exhibit an impaired counterregulatory response to hypoglycemic events, such as a suboptimal release of glucagon, cortisol, and epinephrine, which stimulate glycogenolysis and gluconeogenesis and inhibit insulin secretion." (PMID 39913488, 2025). "In PDAC donors with diabetes, INS positively correlated with both GCG and SST, suggesting a simultaneous loss of multiple endocrine cell types." (PMID 40244011, 2025). "By stabilizing GLP-1R in its active conformation, exenatide enhances glucose-stimulated insulin secretion, suppresses glucagon release, and slows gastric emptying—actions critical for managing type 2 diabetes mellitus." (PMID 41226200, 2025). "The reversibility of diabetes is determined not only by the improvement of insulin resistance but also by the interaction of many parameters such as pancreatic β-cell reserve, glucagon release, gastrointestinal hormones and hepatic steatosis." (PMID 41156143, 2025). "This review synthesizes current knowledge on the secretion mechanisms of insulin, glucagon, somatostatin, ghrelin, and pancreatic polypeptides, emphasizing their functional crosstalk in diabetes." (PMID 40919135, 2025). "Recent studies have identified altered lysosomal trafficking of glucagon as a novel pathway contributing to excess glucagon in diabetes." (PMID 39996055, 2025). "A closed loop artificial pancreas system, both in bihormonal (insulin+glucagon) and insulin-only configuration was compared with usual diabetes care in 3 adult patients." (PMID 38966218, 2024). "We used non-obese diabetic (NOD) mice, a widely used polygenic mouse model of human T1D9,10, to explore why hypoglycaemia-induced glucagon secretion becomes impaired in diabetes." (PMID 39313541, 2024). "Based on this information, it is therefore evident that the interest for the potential role of glucagon in the treatment of diabetes (as well as obesity) is currently outstanding." (PMID 38681771, 2024). "Suppression of miR-23a upregulated insulin level and downregulated glucagon level in STZ-induced diabetes mice models, effectively promoting α-to-β like cell transition." (PMID 38517864, 2024). "In this observational study, we aimed to identify correlations between serum levels of HGF and EGF, insulin, glucagon, glucose, and primary serum lipids in patients with type 2 diabetes mellitus (DM), taking into account the impact of gender." (PMID 38654922, 2024). "A mechanism of action phase 1 study showed that the glycemic efficacy of tirzepatide in T2DM results from concurrent improvements in key components of diabetes pathophysiology, including β-cell function, insulin sensitivity, and glucagon secretion." (PMID 39114288, 2024). "Glucose control in diabetes is regulated in part by glucagon, not only through paracrine intra islet cell communication, but also through peripheral effects on hepatic, adipose and neural metabolism." (PMID 39619323, 2024). "An excess of glucagon relative to insulin characterizes the metabolic dysregulation and hyperglycemia of diabetes." (PMID 39619323, 2024). "Diabetes mellitus involves both insufficient insulin secretion and dysregulation of glucagon secretion." (PMID 39313541, 2024). "Diabetes is a multifactorial disease, but insufficient insulin secretion due to inadequate functional beta cell mass and dysregulated, often increased, glucagon secretion are fundamental to essentially all forms of diabetes and contribute to hyperglycemia." (PMID 39433176, 2024). "Literature suggests that islet hormone secretion is regulated by glucose levels in the blood and decreased secretion during diabetes correlates with disrupted secretion of pancreatic hormones such as insulin, glucagon, and somatostatin." (PMID 38529398, 2024). "Patients with diabetes have been shown to exhibit insufficient suppression of glucagon secretion following oral ingestion of glucose intake or a meal." (PMID 39149119, 2024).